IL2 (interleukin 2)
Diseases named in the same sentence as IL2 in open-access papers (continued):
Sharing a sentence is not in itself a finding about the gene and the disease.
tumor (continued). "In line with tumor immunogenicity induced by itaconate, thimerosal also triggers tumor immunogenicity evidenced by significantly increased IL-2 promoter–driven LacZ activity and IFNγ production in T cells co-cultured with thimerosal-treated tumor cells." (PMID 39349845, 2024). "Tumour immunity is however a complex process, for example the expression of IL2 can both promote T-reg activity for the benefit of tumours, but it can also promote the activity of anti-tumour T-cells." (PMID 38773187, 2024). "This capture of IL-2 by CD25 is vital for the endogenous anti-tumor and anti-viral activity of activated CD8+CD25+ cells." (PMID 38887559, 2024). "These include the fusion of IL-2 to tumor targeting antibodies as well as the fusion to inactivation domains with protease cleavable linkers." (PMID 39114660, 2024). "The phenotypic change of IL-2 or IL-21-supplemented TCR-T during repetitive tumor antigen stimulation was also monitored." (PMID 38643203, 2024). "This targeted IL-2 delivery circuit offers a promising approach to overcome tumor suppression locally and minimize systemic IL-2 toxicity at the same time." (PMID 38904025, 2024). "Cytokines such as IFNγ, IFNα, and IL-2 promote anti-tumor responses in the TME, while dysregulation of cytokines produced by immune, malignant, and stromal cells are involved in the entire process of carcinogenesis and therapy response." (PMID 39507618, 2024). "This establishes a signaling bypass mechanism that induces the production of local IL‐2 upon synNotch's recognition of a tumor." (PMID 39422665, 2024). "The efficacy of IL-2 in T cell immunity is compromised by acidic tumor environments due to reduced STAT5 activation." (PMID 39461979, 2024). "Following isolation, cells are proliferated in vitro using interleukin-2 (IL-2) and then are introduced back into patients in order to produce a robust immune-mediated anti-tumor response." (PMID 38893120, 2024). "In OC lesions, Tregs suppress the immune response to tumor-associated antigens by inhibiting the secretion of interferon-gamma (IFN-γ), interleukin-2 (IL-2), IL-10, and TGF-β by effector T cells." (PMID 39200270, 2024). "Interleukin-2 (IL-2) helps promote tumor cell death by enhancing the survival and expansion of CD4+ and CD8+ T cells as well as natural killer (NK) cells." (PMID 39025948, 2024). "The encapsulation of IL-2 into polymers has also been used for localized delivery of IL-2 to the tumor microenvironment." (PMID 39114660, 2024). "The aim of including IL-2 together with aMUC1aCD3 in TILT-322 is to generate anti-tumor immune responses by accelerating effector CD8+ T and helper CD4+ T cell proliferation in Mucin1 (MUC1)-positive tumors." (PMID 38910324, 2024). "Although it has long been suspected that local conditions from the native tumour microenvironment (TME) restrain the response to IL-2 in tumour-specific TILs, very little is known about which TME factors drive this restriction." (PMID 38658764, 2024). "The numbers of TILs per gram tumor secreting GzmB, IFNγ, TNFα, and IL-2 were considerably higher in both primary and secondary tumor in the hRT/lena treatment group." (PMID 38646638, 2024). "Surgically resected tumor deposits are cultured with high-dose IL-2 to proliferate tumor-infiltrating lymphocytes (TILs)." (PMID 38534309, 2024). "Even though M5A–IL-2 did not improve the antitumor efficacy compared to IL-2–Fc fusion protein, higher tumor uptake and slower blood clearance were observed in M5A–IL-2-treated mice." (PMID 39204319, 2024). "Flow cytometry was utilized to assay immune cell infiltration in patient tumor tissues, while western blot and quantitative polymerase chain reaction (qPCR) assays measured IFN-γ, IL-2, and PD-L1 levels in tumor tissues." (PMID 39641253, 2024).
tumor (continued). "In various transplantable tumor models, the IL-2 mutant demonstrates superior antimetastatic effects compared to wild-type IL-2." (PMID 39169031, 2024). "A pH-sensitive IL-2v (Switch-2) that more potently activated CD8+ T cells in an acidic than neutral environment induced better anti-tumor immune responses with reduced toxicity in normal tissues than native IL-2." (PMID 39114660, 2024). "Nevertheless, other studies have demonstrated that tumor-derived EVs can inhibit the proliferation of CD8+ T cells by lowering the levels of IL-2 or inducing CD8+ T cell apoptosis through mechanisms such as Galectin 9 and the FasL-TRAIL pathway." (PMID 39281673, 2024). "Since Tregs are well known for their immunosuppressive activity favoring tumor progression, development efforts have been made to engineer a recombinant IL-2 with low stimulating activity on Tregs." (PMID 39204319, 2024). "At high doses, IL-2 binds to medium-affinity receptors, activating effector T cells and exerting immune-activating effects, which are employed in anti-tumor therapy." (PMID 38352877, 2024). "Further studies were conducted between IL‐2‐Fc and M5A‐IL‐2 ICK combined with SRT to compare tumor size reduction and generation of immune memory." (PMID 38317590, 2024). "The results revealed that local intracranial administration of IL-13Rα2-targeted CAR-T-cell therapy in combination with recombinant human IL-2 was well tolerated and resulted in transient tumor reduction or necrosis at the infusion site in four patients." (PMID 39406966, 2024). "Trials on IL-2 fusion toxin have demonstrated anti-tumor activity both as a single agent and in combination with other drugs." (PMID 38607023, 2024). "An adenovirus vector carrying human IL-2 gene (AdCAIL-2) was delivered i.t. to tumor cells derived from tumors of MMTV-PyMT transgenic mice which spontaneously develop tumors." (PMID 38803496, 2024). "Infusion of orthoIL-2Rβ pmel-1 T cells followed by treatment with orthoIL-2 1G12 produced a significant tumor growth delay and survival advantage similar to the IL-2 treatment group." (PMID 39114660, 2024). "PGE2 levels are elevated in human tumor tissues and impair IL-2 sensing in human CD8+ T cells by downregulating the IL-2 receptor gamma chain (IL-2Rgc), leading to oxidative stress and ferroptosis in tumor-reactive lymphocytes." (PMID 39402302, 2024). "At least ten clinical trials are currently underway involving IL-2 in combination with tumor-infiltrating lymphocytes (TILs)." (PMID 38545115, 2024). "Subsequently, WB and qPCR were used to measure the expression of IFN-γ, IL-2, and PD-L1 in tumor tissues." (PMID 39641253, 2024). "Based on these data, we decided to utilize a combination of αCD3, αCD137, αPD-1, and IL-2 for the ex vivo tumor cell killing assay, comparing EV-Cis display with equivalent doses of free ligand." (PMID 39033322, 2024). "It has been shown that each tumor model has its own starting distribution of myeloid subpopulations, and It is important to keep in mind that the effects of IL‐2‐Fc and ICK on these starting subpopulations is also model and tissue dependent." (PMID 38317590, 2024). "We also note that one patient initially negative for PD-L1 expression, after two cycles of high dose IL-2, had an increase in tumor cell PD-L1 expression." (PMID 39026970, 2024). "This synNotch–IL-2 circuit allowed CAR T cells to produce IL-2 in a limited manner at the tumor site and activate themselves in an autocrine manner, which helped to overcome the immunosuppressive environment." (PMID 38491394, 2024). "More recently, it was also shown that Tph1 was induced in response to IL-2 in T cells in tumor microenvironment, leading to AhR nuclear translocation." (PMID 38509264, 2024). "Unbiased PEG-IL-2 has been shown to have improved in vivo efficacy over native IL-2 in murine tumor models." (PMID 39114660, 2024).
tumor (continued). "CD8+ TIL polyfunctionality was predicated on coordinate CD8+ TIL responder intracellular expression of IFNγ, TNFα, and IL2 as determined by flow cytometry after a 5 h in vitro stimulation with either tumor cells or PVECs." (PMID 39066414, 2024). "Through the regulation of immune responses and reinforcement of antitumor effects, these interventions influence the levels of Th1, Th17, and Th2 cytokines, augmenting IL-2, tumor TNF-α, IFN-γ, and IL-17A, while diminishing IL-10 levels." (PMID 38794206, 2024). "MiR-24-1-5p expression was negatively correlated with tumor-related immune suppression pathways such as the IL2/STAT5 and IL6/JAK/STAT3 signaling pathways." (PMID 38840234, 2024). "The anti-PD-1-IL-15m (PF-07209960) was designed to deliver PD-1-mediated and avidity-driven IL-2/15 receptor stimulation to PD-1 positive tumor-infiltrating lymphocytes while minimally affecting circulating peripheral NK and T cells." (PMID 39204319, 2024). "After 22 days, with IL-2 injections 3x/week, mice were imaged to determine the presence of K562-Luc tumor cells." (PMID 38711506, 2024). "In summary, the combination of high-dose radiation therapy with RDB 1462-engineered IL-2 profoundly impacted tumor growth, metastasis, and the immune response in the experimental mouse model." (PMID 39218928, 2024). "In this study, we developed a method to generate TITR mimics from peripheral blood mononuclear cell (PBMC)-derived Tregs, employing CD3/CD28 activator, interleukin 2 (IL-2), vitamin D3 (VitD3) and tumor cell-conditioned medium (TCM)." (PMID 38231448, 2024). "A similar mechanism in the tumor microenvironment induced CD8+ T cell exhaustion via IL-2-mediated STAT5 activation and tryptophan hydroxylase-1 expression, leading to AhR activation." (PMID 39211042, 2024). "Numerous studies have explored anti-tumor strategies targeting CD25 or combining IL-2 with cytotoxic molecules or CD25-ADC (antibody-drug conjugate) to deplete Treg cells." (PMID 38500876, 2024). "The fusion of an anti-FAP antibody to IL2v allows for increased localized IL2v exposure in FAP-positive tissues in the tumor microenvironment; however, free or unbound FAP-IL2v can still bind to IL2Rβγ in other tissues, causing IL2-related adverse effects." (PMID 39140264, 2024). "Decreased IFN-γ and IL-2 levels were observed in tumor-infiltrating CD4+ T cells from the Id2fl/flCd4-Cre+ mice compared with the Id2fl/flCd4-Cre− mice, while no such differences were observed in CD8+ T cells." (PMID 38287103, 2024). "In the PDA7940b tumor model, significantly more IL-18, IFNγ, and IL-2 was detected in mouse serum from the combination treatment group comparted to CART alone." (PMID 38730243, 2024). "Based on the SPR results, we expected that MB2033 would demonstrate greater functional affinity for hPD-L1 expressed on tumor cells relative to its affinity for IL-2Rs on immune cells when compared with WT IL-2-based immune cytokines." (PMID 38834889, 2024). "A small SC134-TCB–induced increase in IFNγ and IL2 was detectable, potentially already reflecting tumor target–mediated cytokine production." (PMID 39186309, 2024). "Melittin‐MIL‐2 can enhance the anti‐tumor immune effect of recombinant IL‐2 (rIL‐2) monomer and reduce the toxic side effects of rIL‐2 alone." (PMID 39003635, 2024). "When compared with standard IL-2-expanded TILs, TILs expanded from COXi-treated tumour fragments exhibited higher surface expression of IL-2Rγc, predicting restored responsiveness to IL-2." (PMID 38658764, 2024). "In order to investigate the role of IL-2 in DCs for tumor adoptive cell therapy, we isolated DCs from human peripheral blood." (PMID 38554155, 2024). "Immune cell infiltration of the tumor and the release of interleukins (IL), specifically IL-2, IL-6, and IL-8, tumor necrosis factors, and interferons have proven their immunomodulatory effects in a number of studies." (PMID 39507201, 2024).
tumor (continued). "Nonetheless, the evidence for the expression of NKp30 under the regulation of IL-2 has been less elucidated so far in the context of human NK cell cytotoxicity against tumor cells." (PMID 38698855, 2024). "In vivo studies in male mice also reveal that administration of vitamin C, a promising anti-cancer agent, stimulates TET2 activity, induces tumor vascular normalization and enhances the efficacy of anti-PD-L1 therapy alone or in combination with IL-2." (PMID 38177099, 2024). "The anti-PD-L1 × IL-2v fusion protein, conceived upon an innovative bispecific antibody platform, addresses the limitations of conventional IL-2 therapies by mitigating adverse effects while enhancing anti-tumor efficacy." (PMID 38834889, 2024). "While TPV/eGFP and TPV/∆66R/m-IL-2/mCherry demonstrated a trend of regressed tumor volume over the course of the study, both recombinants failed to reach statistical significance." (PMID 39200298, 2024). "IL-2 is an essential cytokine for lymphocytes, including NK cells, to survive and sustain anti-tumor function and has been approved for the treatment of metastatic melanoma and metastatic renal cell carcinoma as a form of monotherapy." (PMID 38698855, 2024). "Stable Tregs promote the death of Th2 cells by CTLA-4 expression and competing for IL-2, which plays a crucial role in inhibiting Th2 cells from promoting tumor growth and metastasis." (PMID 38509593, 2024). "Kartono24 arrived at own mathematical model that describes influence of Interleukin-2 (IL-2), interferon-alpha, and tumor-infiltrating lymphocytes on the activity of the tumor cells." (PMID 39009619, 2024). "The interaction between TIM3 and galectin 9 (Gal9) in CD8+ T cells leads to the reduction of the production of cytokines (IFNγ, IL-2, and TNFα), the inhibition of T cell proliferation, and the inhibition of anti-tumor immunity." (PMID 39372416, 2024). "They showed that conjugation of an α-hPD-L1 antibody to dendrimers improved PD-L1 binding by up to an order of magnitude which correlated with the rescue of IL-2 production in a Jurkat co-culture model and increased tumor accumulation." (PMID 38685532, 2024). "Tumor fragments are then cultured alone in the presence of high-dose IL-2 (6,000 IU/mL) for 3–5 weeks prior to REP." (PMID 39238638, 2024). "The combination of αCD3, αCD137, αPD-1, and IL-2 demonstrated the most potent effect, achieving over 90% tumor cell death following 6 days of co-culture." (PMID 39033322, 2024). "In the context of the oncolytic reovirus model, hyperactive NK cells in mice preconditioned with IL-2 and Treg-depleting antibody display increased extravasation, transmigration, and tumor infiltration, which led to increased reovirus localization." (PMID 39066359, 2024). "For example, at a high (5:1) E:T ratio, NT‐T cells supplemented with IL‐2 induced as much tumor cell killing as FAP‐CAR‐T cells." (PMID 38975278, 2024). "IL-2 has been shown to play a vital role in the regulation of CD8+ T-cells to maintain their reactivity against tumor cells." (PMID 38346068, 2024). "In matched patient-derived xenografts (PDX) models, homologous TILs efficiently reduced tumor size (p < 0.0001) and underwent IL-2 absence in vivo." (PMID 38769543, 2024). "This binding causes lymphocytes to release cytokines IL-2, IL-1b, IL-6, TNF and Ifny into the medium, which leads to the appearance of cytotoxic lymphocytes in PBMC capable of lysing HLA-negative tumor cells." (PMID 38203798, 2024). "Asparaginase deletion was able to restore, or even enhance, IL-2 production in our co-culture model and within primary tumours." (PMID 39558103, 2024). "Analysis of T-cell profiles from CD83OE tumor mice in vivo revealed an increase in IL-2 expression and the largest proportion of TNFα-producing cells." (PMID 39601621, 2024). "Among them, TNF‐α and IL‐2 are produced by Th1 cells and mediate anti‐tumour effects, while Th2 cells produce IL‐6 and IL‐10 and promote tumour growth by suppressing the immune system." (PMID 38451046, 2024).
tumor (continued). "Animal models have demonstrated the impressive anti-tumor effects of the IL-2 split mimic, potentially revolutionizing cancer therapy in the future." (PMID 39169031, 2024). "Since our in vitro data suggest that expansion with IL-2 over time compromises the anti-tumor activity of WT CD8 CAR-T cells, we tested the in vivo anti-tumor efficacy of WT and MCJ KO CD8 CAR-T cells that were expanded with IL-2 only for one expansion." (PMID 38789421, 2024). "Tumor growth was significantly inhibited by T cells activated by DCs co-cultured with PBMCs in the presence of IL-2." (PMID 38554155, 2024). "In accordance, stimulation of primary tumours from infected mice ex vivo exhibited a reinvigorated T cell IL-2 response when asparaginase was deleted from the bacterium." (PMID 39558103, 2024). "The TSR in the P-IL-2 and Palbociclib combination group was 74.08%, with a 1.34-fold increase in tumor suppression and a 1.73-fold reduction in tumor volume compared to the IL-2 and Palbociclib combination group." (PMID 38352877, 2024). "Recently, one study revealed that lenalidomide targets the CRL4CRBN ubiquitin ligase to activate the Notch and interleukin-2 pathways in tumor-infiltrating CD8+ T cells." (PMID 39634262, 2024). "We subsequently co-cultured for 36 h the polarized macrophages with sub-optimally activated T cells (CD3/CD28 and IL-2) isolated from spleens of non-tumor-bearing mice." (PMID 38302493, 2024). "Together, our findings from patient-derived tumour tissues suggest a key role for intratumoral PGE2 in restraining the expansion capacity of cancer-specific human TILs through regulation of their IL-2 responsiveness." (PMID 38658764, 2024). "Overexpression of BCL-2 interferes with normal apoptotic signaling, increasing cell survival following IL-2 withdrawal and preserving T-cell capability to target tumor cells." (PMID 38891056, 2024). "Tumor regression was thus seen in 2 out of 5 patients who had previously had therapeutic failure with IL-2." (PMID 39712007, 2024). "Levels of IFN-γ and IL-2 in the peripheral blood of the tumor-bearing mice in each group were measured." (PMID 38312647, 2024). "Meanwhile, we observed DCs cultured with PBMCs, and IL-2 promoted anti-tumor capacity by producing increased CD8 + cells and Th1 cells but reduced Tregs." (PMID 38554155, 2024). "Anti-CD3, anti-CD28 and IL-2 preactivated immune cells were co-cultured with LLC or SJT1601 tumor cells directly for 24 h or 48 h in vitro, and then suspended cells were collected for flow cytometry." (PMID 39004699, 2024). "The primary aim of this trial was to compare survival without relapse and overall survival of patients receiving either TILs and interleukin (IL)-2 together or IL-2 alone as adjuvant treatment after complete tumour excision." (PMID 39508576, 2024). "In this study, we used a stepwise CRISPR/Cas9 screens in combination of proteomic analyses to identify a CUL5-E3 ligase complex as an important negative regulator of TCR/IL2 signaling and anti-tumor effector activity in CD8+ T cells." (PMID 38242867, 2024). "A pH-selective IL-2 variant, Switch-2, has been engineered to activate CD8+ T cells more effectively in acidic conditions, enhancing anti-tumor responses and minimizing toxicity in normal tissues." (PMID 39461979, 2024). "Despite numerous conflicting reports on the impact of CD4 + Th1 cells on the survival outcomes of PDAC patients, mechanistically, these cells are linked with key cytokines IL-2, IFN-γ, and TNF-α, contributing to anti-tumor immunity." (PMID 38833018, 2024). "Tumor material is then shredded into fine particles and incubated with high levels of IL-2, achieving isolation of the initial lymphocyte population." (PMID 39682188, 2024). "Tumor myeloid subpopulations were analyzed from the studies above to further explore the different mechanisms underlying the antitumor effects of ICK and IL‐2‐Fc." (PMID 38317590, 2024).